CCN5 (cellular communication network factor 5)
Diseases named in the same sentence as CCN5 in open-access papers (continued):
Sharing a sentence is not in itself a finding about the gene and the disease.
tumor (continued). "Given the tumor suppressor and anti-invasive roles of CCN5 in BC, we used molecular techniques to investigate whether leptin has any influence on CCN5 to promote BC progression." (PMID 29370782, 2018). "Additionally, therapies aimed at upregulating CCN5 and E-cadherin expression levels might be explored as potential approaches to inhibit tumor progression and metastasis, providing new insights for targeted therapies." (PMID 39144722, 2024). "Interestingly, the effects of recombinant CCN2 peptide on U-CH1 cells were more pronounced under normoxia than hypoxia, promoting increased expression of CCN1, CCN2, CCN3 and CCN5, the notochord-associated markers SOX5, SOX6, T, CD24, and FOXA1 as well as increased tumour-sphere formation." (PMID 25541962, 2014). "CCN5 (also known as WISP-2, HICP, rCOP1, or CTGF-L) is a 29 kD secretory protein and a member of the CCN family that also functions as a tumour suppressor gene." (PMID 40016720, 2025). "CCN5 (also known as WISP-2) is a member of the CCN family and involved in angiogenesis, cell proliferation, differentiation, apoptosis, and tumor formation." (PMID 39144722, 2024). "Compared to fibroblasts from normal tissues, the top upregulated genes in tumor-derived fibroblasts were CXCL8, CXCL2, CCL2, CXCL3 and CXCL1, and the top downregulated genes were IGFBP5, PTGDS, CCN5, CFD, and RAMP1." (PMID 36357663, 2022). "We demonstrate that EGCG activates CCN5 to inhibit in vitro cell viability through apoptosis, the sphere‐forming ability via reversing TNBC cells’ stemness, and suppressing tumor growth in vivo." (PMID 33745223, 2021). "In contrast, ectopic expression of CCN5 in TNBC cells reduced growth/proliferation, tumor-forming ability, invasiveness and sensitivity to tamoxifen by activating ER-α, demonstrating similarities to ER-α positive, non-aggressive BC cells." (PMID 29370782, 2018). "Our previous study has shown confined staining of CCN4, CCN5 and CCN6 at the cell membrane in normal colorectal epithelial cells, while an increased staining of CCN4 and CCN6 was seen in CRC tumours." (PMID 28412738, 2017). "Membrane staining of CCN4, CCN5 and CCN6 were reduced in CRC tumours, with an elevated cytoplasmic staining of CCN4 and CCN6 but not CCN5." (PMID 28412738, 2017). "The overexpression of CCN5 in SP results in EMT reversion, ER-α upregulation and delays in tumor growth in xenograft models." (PMID 28450698, 2017). "CCN5, also known as WISP-2, belongs to the CCN family of proteins and participates in diverse cellular functions, including angiogenesis, cell proliferation, differentiation, apoptosis, and tumor formation." (PMID 39144722, 2024). "Based on these novel observations, we may conclude that the reactivation of CCN5 in TNBC by EGCG provides a potentially unique therapeutic strategy for eliminating the residual tumor cells and preventing tumor growth and recurrence." (PMID 33745223, 2021). "We reasoned that CCN5 distinguishes SP and NSP and could reprogram SP to NSP transition, thereby delaying tumor growth in the xenograft model." (PMID 28450698, 2017). "Since EGCG treatment resulted in proliferating cell nuclear antigen (PCNA) downregulation and activation of CCN5 in tumor tissues, tumor growth inhibition could be mediated via suppressing PCNA, a protein that actively participates in cell cycle regulation and apoptosis, and CCN5 activation." (PMID 33745223, 2021). "In addition, CCN5 restored ER-α, reprogramed mesenchymal-epithelial transition (MET) and blocks TIC’ turnover that may impair tumor progression." (PMID 28450698, 2017). "Collectively, these studies suggest that CCN5 blocks self-renewal capacity of SP cells as well as de-differentiates SP to constituent cancer cells (like NSP) via reversing EMT, stemness and restoring ER-α and thereby SP cells lost their tumor initiating skills." (PMID 28450698, 2017).
tumor (continued). "Except for CCN5 and CCN6, which have not been studied in this context, all CCN protein family members have been associated with hematologic malignancies and often, but not always, their expression is increased in either tumor cells or in stromal cells, mostly displaying pro-tumor effects." (PMID 33428075, 2021). "To corroborate these findings, we isolated tumor-initiating side populations (SP) and non-side population (NSP or main population) from MCF-7 cell line, and evaluated the impact of CCN5 on these subpopulations." (PMID 28450698, 2017). "In addition, induction of CCN1/Cyr61 and CCN5/WISP2 was also found in the CCA tumors, whereas CCN3/NOV and CCN6/WISP3 did not have obvious changes in both the nontumor and tumor samples from the CCA tissues." (PMID 27829832, 2016).
cancer (33 papers, 2009 to 2025). A tumor composed of atypical neoplastic, often pleomorphic cells that invade other tissues. "High CCN5 expression was associated with shorter OS in four types of cancer (COAD, KIRC, KIRP, and STAD) and longer OS only in SARC, suggesting that CCN5 acts as an anti-oncogene." (PMID 33833779, 2021). "Our recent studies indicate that deficiency of the CCN5-driven program in BC promotes the growth of cancer cells and EMT, while upregulation of CCN5 is linked with ER-α-activation in both normal and cancer cells of human and mouse breast." (PMID 29370782, 2018). "Since EMT and cancer stemness are associated with invasion and solid tumor progress, we measured the effect of CCN5 treatment on TNBC cell in vitro migration using modified Boyden chamber assay." (PMID 28450698, 2017). "We first assessed expression of CCN family members, CCN1, CCN2, CCN3 and CCN5 which have been implicated in modulating cell proliferation, cell adhesion, angiogenesis, cell migration, metastasis and epithelial-mesenchymal transition in a variety of cancers." (PMID 25541962, 2014). "In cancer models such as breast and pancreatic carcinoma, CCN5 exerts its biological effects through autocrine or paracrine mechanisms to modulate WNT signaling and other pathways, particularly influencing the endothelial–mesenchymal transition process." (PMID 40756763, 2025). "ccn5 (−9.05 fold) is a cellular communication network factor relevant to the connective tissue growth factor family and involved in the regulation of cancer progression." (PMID 41227295, 2025). "GSEA further revealed significant activation of several fibrosis-related terms, such as “Cell adhesion molecules”, “Proteoglycans in cancer”, and “Mesenchymal cell proliferation” in the Rec-CCN5 incubation group." (PMID 40756763, 2025). "Although all CCN family members (except CCN5) have four highly conserved functional domains, they have different roles within particular types of cancer." (PMID 33833779, 2021). "The results of these bioinformatics analyses suggest that CCN5 expression and function vary across different types of cancer, perhaps due to differences in its structure compared with other CCN family members." (PMID 33833779, 2021). "Multiple studies from our laboratory and others have shown that CCN5-signaling plays a vital role in orchestrating the growth and behavior of cancer cells." (PMID 29370782, 2018). "CCN5 mRNA levels also vary across different types of cancer." (PMID 33833779, 2021). "CCN5 acts as an anti-invasive element in cancer cells of the breast, pancreas and GI tract." (PMID 29370782, 2018). "Recent studies have uncovered that WISP-2/ CCN5 can have an impact on the survivability, expression of ER-α, and stem cell-like qualities found in TNBC and additional forms of cancer." (PMID 37838685, 2023). "CCN5/WISP‐2 is a gatekeeper gene that regulates viability, ER‐α, and stemness in TNBC and other types of cancers." (PMID 33745223, 2021). "Using MCF-7-SP cells as a model for TICs/CSCs, we investigated the status of CCN5 in SP and NSP descendants (constituent cancer cells)." (PMID 28450698, 2017). "It has been shown that the absence of CCN5 drivers in BC promotes cancer cell growth and EMT, whereas up-regulation of CCN5 is associated with ER activation in normal and cancerous cells in human and mouse mammary glands." (PMID 40016720, 2025).
metabolic disorders (5 papers, 2018 to 2025). "This study seeks to provide a comprehensive understanding of the intricate relationship between CCN5 and metabolic disorders." (PMID 37794318, 2023). "Furthermore, it was observed that the transcription of the CCN5 gene exhibited heightened activity within the subcutaneous adipose tissue of individuals affected by metabolic disorders." (PMID 37794318, 2023).
infection (2 papers, 2018 to 2025). The state of being infected such as from the introduction of a foreign agent such as serum, vaccine, antigenic substance or organism. "Restoration of the CCN5 level via infection of a recombinant adenovirus harboring CCN5 (AdCCN5) prevented and reversed TGF-β-mediated fibrotic deformation of RPE cells." (PMID 30571728, 2018).
brain diseases (1 paper, 2025). "While the roles of PAEP, CCN5, and XG in brain diseases are not yet fully understood, our study identifies significant associations between these proteins and brain structure, offering a valuable basis for future studies." (PMID 40456753, 2025).
CCN5 also shares sentences with these, for which no sentence is quoted: esophageal cancer (4 papers); colon cancer (3); hepatocellular carcinoma (3); ovarian carcinoma (3); atherosclerosis (2); atypical ductal hyperplasia (2); colorectal cancer (2); pancreatic adenocarcinoma (2); adenocarcinoma (1); astrocytomas (1); bladder cancer (1); bladder tumors (1); cholestasis (1); Cirrhosis (1); clear cell carcinoma (1); clear-cell renal cell carcinoma (1); colon adenocarcinoma (1); Cushing syndrome (1); Deep Venous Thrombosis (1); endometrioid carcinoma (1); endometriosis (1); esophageal squamous cell carcinoma (1); esophagitis (1); gestational diabetes mellitus (1); glaucoma (1); glioma (1); Glucose intolerance (1); hematologic malignancies (1); Hyperglycemia (1); Hyperinsulinemia (1).
A further 33 diseases each share a sentence with CCN5 in 1 paper.